TNF (tumor necrosis factor)
Diseases named in the same sentence as TNF in open-access papers (continued):
Sharing a sentence is not in itself a finding about the gene and the disease.
COVID-19 (continued). "Meanwhile, previous studies showed that patients with COVID-19 were in a pro-inflammatory status with high levels of IL-1β and other cytokines, and high levels of IL-6 and TNF-α were observed in COVID-19 patients requiring intensive-care-unit hospitalization." (PMID 34863291, 2021). "In an early study on 41 COVID-19 patients, those with severe disease had higher levels of D-Dimer along with high levels of IL-8, TNFα and IL-2R." (PMID 34367726, 2021). "Overproduction of inflammatory cytokines is a keystone event in COVID-19 pathogenesis; TNF and its receptors (TNFR1 and TNFR2) are critical pro-inflammatory molecules." (PMID 34445140, 2021). "Elevated levels of inflammatory cytokines such as IL-6 and TNF-α have also been shown in the CSF of COVID-19 patients with neurological presentation, indicating an ongoing inflammatory process in the brain." (PMID 34680490, 2021). "From serum analysis, we found that the levels of IL-6 and TNF-α on admission time were higher in children with COVID-19 compared to the other groups, in line with previous studies performed on adults." (PMID 34578450, 2021). "IFN gamma and TNF alpha drive macrophages of an abundant inflammatory phenotype to the lung in severe COVID-19-cases." (PMID 34149697, 2021). "Anti-TNF agents are regarded as both recommended therapies for IBD and potential therapies for cytokine storms caused by COVID-19." (PMID 34335579, 2021). "COVID-19 is characterized by increased levels of numerous cytokines, mainly of proinflammatory character, including tumor necrosis factor-alpha (TNF-alpha), interleukin-6 (IL-6), and CRP." (PMID 34946334, 2021). "The high concentration of COVA1-18 immune complexes elicited substantially less IL-1β, IL-6, and TNF than anti-spike immune complexes made from COVID-19 serum." (PMID 33979301, 2021). "In severe COVID-19 systemic levels of pro-inflammatory cytokines, such as tumor necrosis factor-α (TNF-α) and interleukin (IL)-1 and IL-6, are markedly increased." (PMID 33368021, 2021). "For the majority of these cytokines and chemokines, including those that are typically associated with MAS (IL-6, IL-18, IFN-γ, TNF-α, CXCL9) the increase was less pronounced in COVID-19 critical condition than in MAS patients." (PMID 34226537, 2021). "In spite of the recommendation by some medical societies against the initiation or continuation of bDMARDs (including anti-TNF drugs) in the places where COVID-19 has been circulating in the community, the use of anti-IL-6 agents has been regarded to be safer." (PMID 34943795, 2021). "Assess Efficacy of HB-adMSCs to treat COVID-19 patients.Primary endpoints: detect change from baseline in inflammatory markers (IL-6, IL-10, TNF-alpha, C Reactive protein), improving oxygenation, and decreasing time to return to room air (RTRA)." (PMID 33815867, 2021). "Both post COVID-19 groups had significantly higher dp TNFα+ IL-2+ SARS-CoV-2 S N-term reactive CD4+ T cells compared to HC (Ab−: p = 0.04; Ab+ p = 0.05)." (PMID 34322120, 2021). "Monocyte/macrophage activation syndrome was reported in severe COVID-19 cases, with interferon-γ (IFNγ), interleukin-1 (IL-1), IL-6, tumor necrosis factor-α (TNFα), and IL-18 having central immunopathogenic roles in the hyper-inflammation." (PMID 34578386, 2021). "Via the TLR9 pathways, a plethora of inflammatory mediators and cell types can be triggered such as interleukin-6 (IL-6) and tumor necrosis factor (TNF)-α in severely ill patients with COVID-19." (PMID 36303774, 2021). "The level of these cytokines was also elevated in nasopharyngeal swabs of severe COVID-19 patients compared to healthy controls (for TNF-α, IL-1β and IL-1A, for IL-6, IL-8 and IL-23)." (PMID 33995033, 2021). "Compared with patients in severe COVID-19, those who in critical COVID-19 had significantly higher levels of tumor necrosis factor-α (TNF-α), interleukin-6 (IL-6), IL-8, and IL-10." (PMID 34725309, 2021).
COVID-19 (continued). "For example, IR HUVEC showed a significantly higher production of various inflammatory cytokines as IL6, G-CSF, and TNFα, known markers of a poor prognosis in severe infectious conditions including COVID-19." (PMID 34375950, 2021). "CXCL10, interleukin (IL-15) and interferon (IFN-g) are increased after a COVID-19 vaccination with a BNT162b2 mRNA (Pfizer/BioNTech) vaccine and are enriched by tumor necrosis factor alpha (TNF-α) and IL-6 after the second vaccination." (PMID 34835155, 2021). "TNF-α levels in the serum of COVID-19 patients increase at the time of admission (3-5 days after infection), which continue until day 3 after admission." (PMID 35126355, 2021). "The observed pronounced inhibition of TNFα and IL-6 is the most important finding, because these molecules are currently considered to be the main targets in COVID-19 cytokine storm and ARDS pathogenesis." (PMID 33465050, 2021). "The results of the KEGG pathway analysis showed that AKT1 was involved in the treatment of COVID-19, mainly by regulating TNF and other signaling pathways." (PMID 34077310, 2021). "Observational registry data from patients with inflammatory bowel disease who contracted COVID-19 suggest a possible benefit from taking anti-TNF medication in terms of a composite outcome of death or hospital admission, however not with either outcome alone." (PMID 34341776, 2021). "Spike-stimulated PBMCs exhibited high CD8+ T-cell frequencies, with IFN-γ, IL-2, and TNF production in COVID-19." (PMID 34571855, 2021). "After SARS-CoV-2 infection, vascular endothelial cells become dysfunctional and IL-6, TNF-a, and MCP-1 levels are elevated, leading to COVID-19-associated vascular inflammation and coagulopathy, particularly endotheliitis in the lungs, heart and kidney." (PMID 34344353, 2021). "Meanwhile, increased serum levels of IL-2, TNF-α, IL-7, granulocyte-colony stimulating factor and interferon-γ inducible protein 10 (CXCL10) are associated with COVID-19 disease severity." (PMID 33581688, 2021). "TNF-α inhibitors such as adalimumab and golimumab can also be employed to manage COVID-19-induced hyperinflammatory response." (PMID 34066983, 2021). "In this pilot study we investigated the serum levels of sTNFRI and TNF-α in COVID-19 patients who either required ICU treatment or patients with milder disease who were not treated within the ICU." (PMID 33968010, 2021). "COVID-19 patients with severe respiratory symptoms had higher levels of Tumor necrosis factor-α (TNF-α) and IL-645." (PMID 34413339, 2021). "This was especially seen with severe COVID-19, and displayed as high plasma levels of inflammatory cytokines such as IL-2, IL-7, IL-10, and tumor necrosis factor (TNF)." (PMID 34046852, 2021). "The percentage of CD16Int LDNs, however, showed a significant positive correlation with TNF-α and IL-6 levels across all COVID-19 patients." (PMID 33986193, 2021). "Since a cytokine storm is one of the complications of COVID-19, some of the MAbs are also targeted against proinflammatory mediators, such as TNF-α, IL-4, and IL-10." (PMID 34769383, 2021). "A large study that enrolled 1500 hospitalized COVID-19 patients, demonstrated that serum levels of IL-6, IL-8, and TNF-α were elevated at the time of admission and correlated with mortality." (PMID 34945111, 2021). "Plasma levels of IL-6, TNFα, IL-1β, IL-10 and IL-21 were significantly higher in Asymptomatic COVID-19 cases as compared with Controls." (PMID 34824360, 2021). "In COVID-19 patients, a pro-inflammatory status with high levels of IL-1β, IL-6 and TNF-α have been demonstrated." (PMID 34313585, 2021). "This disruption of cell–cell interactions by TNFα was, at least partially, prevented by co-incubation with HDLs isolated from non-COVID-19 subjects (HDL-) whereas HDL from COVID-19+ patients (HDL+) had no protective effect." (PMID 33504824, 2021).
COVID-19 (continued). "Poor outcomes are generally ascribed to the development of this cytokine storm, and elevated serum levels of TNFα, IL-6, and IL-8 are independent predictors of COVID-19 disease severity and death (3, –5)." (PMID 34479991, 2021). "Compared to patients with moderate COVID-19, patients with severe/critical infections have much higher levels of inflammatory cytokines, particularly interleukin IL-6, IL-1β, and TNF-α, in their BALF and lung tissue." (PMID 33468250, 2021). "Three important cytokines involved in these processes are TNF-α, IL-1, and IL-6, which were increased in COVID-19." (PMID 34177896, 2021). "detected 10 cytokines (including IFN-γ, IL-1α/β, IL-2, IL-6, IL-15, IL-18, IL-33, and TNF-α/β) that were upregulated in patients with moderate or severe COVID-19 compared with the samples from healthy individuals." (PMID 34737743, 2021). "Recently, the global COVID-19 pandemic has brought attention to the devastating effects of cytokine storms, with one study finding that TNFα and IFNγ synergize to trigger inflammatory cell death and increased mortality in SARS-CoV-2 infection." (PMID 33617447, 2021). "In COVID-19 patients a pro-inflammatory status with high levels of IL-6, IL-1B and TNF-α has been demonstrated." (PMID 34313585, 2021). "Severe COVID-19 patients present a “cytokine storm” with cytokine release of interleukins, such as IL-1, IL-6, tumor necrosis factor (TNFa), and other inflammatory mediators, leading to a pulmonary inflammatory response making oxygenation challenging." (PMID 34770225, 2021). "Some patients with COVID-19 develop a cytokine storm syndrome, characterized by overproduction of early response pro-inflammatory cytokines such as tumor necrosis factor, interleukin [IL]-6, and IL-1β." (PMID 35071250, 2021). "Several studies have been published to date that identify clinical features in severe COVID-19 patients such as elevated IL-2, IL-6, TNF-α and IFN-γ, that can resemble the cytokine profile seen in HLH." (PMID 33803997, 2021). "In this study, we investigated the effect of anti-TNF-α monoclonal antibody therapy on the cellular entry mechanism of SARS-CoV-2 and the risk of COVID-19 development." (PMID 34025650, 2021). "Inhibition of TNF-α signaling: TNF-α is an important proinflammatory cytokine primarily produced by activated macrophages and contributes to the COVID-19 hyperinflammatory state." (PMID 34803441, 2021). "The IFN system caused by TNF-a and IFN-g mirrors the tissue damage and inflammation that occur in COVID-19 samples, and most GO and pathway enrichment analyses based on gene expression data have revealed that interferon terms are enriched in COVID-19 patients." (PMID 34777369, 2021). "A common clinical complication associated with COVID-19 is acute respiratory distress syndrome (ARDS) attributed to a cytokine storm of IL-1β, IL-6, IFN-γ, and TNF, among others." (PMID 34445140, 2021). "Previous studies have shown that tumor necrosis factor-α (TNFα) has a significant role in COVID-19 pathology; it activates macrophage, increases cytokine release, and worsens the patient’s condition." (PMID 34441802, 2021). "PPI network for the immunity and inflammation cytokines in COVID-19 among R. crenulata targets showed that IL-10, IL-6, IL-1B, TNF-α, CCL2 and CXCL8 were important nodes in the network." (PMID 34313585, 2021). "Our data showed that, compared with control subjects, COVID-19 patients have elevated levels of TNF-α and IL-1β." (PMID 34253708, 2021). "Increased levels of proinflammatory cytokines, including IL-2, IL-6, IL-7, IL-10, IFNγ, and TNF-α, are commonly observed in patients with severe COVID-19." (PMID 34001144, 2021). "Myeloid hyperinflammation causing lung and peripheral tissue damage via secretion of inflammatory cytokines such as IL-6 and tumor necrosis factor (TNF) in COVID-19 has been reported and in our analysis were primarily expressed by tissue rather than blood MPs." (PMID 33879890, 2021).
COVID-19 (continued). "To mimic a pro-inflammatory environment as it would occur in COVID-19 patients, we pre-incubated endothelial cells with TNF-α or interferons for 24 h prior to infection." (PMID 34224022, 2021). "TNF induced the production of IL-6 and other cytokines, involved in the process of cytokine storm in COVID-19." (PMID 34313585, 2021). "A previous study displayed that serum levels of IL-6, IL-10, and TNF-α increase with disease severity in patients with COVID-19." (PMID 35155477, 2021). "COVID-19 children had elevated levels of IFNγ, IL-2, TNFα, IL-1α, IFNα, IFNβ, IL-6, IL-17A and IL-10 in comparison to seropositive and/or control children." (PMID 33813138, 2021). "Cells stimulated with TNF-α and IFN-γ show MLKL and RIPK1 phosphorylation, suggesting that necroptosis is implicated in the COVID-19 cytokine storm." (PMID 34594225, 2021). "In conclusion, both active AOSD and severe COVID-19 patients showed elevated Gal-3, Gal-9, and cytokines, including IL-1β, IL-1Ra, IL-10, IL-6, IL-18, and TNF-a, supporting a common link of cytokine storm in the pathogenesis of both diseases." (PMID 34367188, 2021). "Based on these premises, we conducted a retrospective assessment of monocyte intracellular TNF-α expression (iTNF-α) and on the frequencies of lymphocyte sub-populations in twenty-five patients with moderate/severe COVID-19." (PMID 34439967, 2021). "IL-6, IL-8 and TNF-α concentrations were significantly lower in COVID-19 groups compared to burn patients." (PMID 33921604, 2021). "The levels of serum proinflammatory cytokines and chemokines were also found to increase in patients with COVID-19, including tumor necrosis factor α (TNF-α), interferon-γ (IFN-γ)-induced protein 10 (IP-10), interleukin-6 (IL-6), IL-8, and IL-10." (PMID 33937333, 2021). "A cytokine profile resembling sHLH is associated with COVID-19 severity, characterized by enhanced IL-2, IL-7, INF-γ, MCP-1, MIP-1α, and TNF-α." (PMID 33670394, 2021). "TNFα was decreased in P2 and P5 compared to HC, but increased in P4 compared to COVID-19 ICU patients." (PMID 34531865, 2021). "Previous results from our group have shown that circulating IL-6 and IL-10 were lower, while TNF-α and IL-8 levels were higher, in the same critically ill COVID-19 patients compared to the critically ill non-COVID-19 patients." (PMID 34575667, 2021). "Disease severity in COVID-19 is associated with a cytokine storm due to higher concentrations of GCSF, IP10, MCP1, MIP1A, and TNF-α, which are associated with higher ICU admissions." (PMID 33884042, 2021). "TNFα and IFNγ are known to particularly drive COVID-19 disease severity and in addition, IL-6, IL-1β and IL-12 have been consistently implicated in severe disease." (PMID 33813138, 2021). "There is increasing evidence that cytokines such as IL-6, IL-1 beta, IFN-gamma and TNF-alpha play important role in pathogenesis of cytokine storms in COVID-19." (PMID 34804738, 2021). "In this study, we investigated the effect of anti-TNF-α monoclonal antibodies on the cellular entry mechanism of severe acute respiratory syndrome coronavirus 2 (SARS-CoV-2) and increasing the risk of COVID-19 development." (PMID 34025650, 2021). "We demonstrated that the CXCL10+ CCL2+ macrophages from severe COVID-19 lungs share a transcriptional phenotype with macrophages stimulated by TNF-α plus IFN-γ." (PMID 33879239, 2021). "In severe COVID-19 infected individuals, interleukin (IL)-6, IL-10, and TNF-α are significantly higher, and it is known that proinflammatory cytokines and chemokines contribute to the occurrence of ARDS." (PMID 33467466, 2021). "Increasing MDSCs during the early stages of COVID-19 were correlated with IL-1β, IL-6, IL-8, and TNF-α plasma levels, particularly in patients who required intensive care treatments, suggesting new therapeutic options geared toward MDSCs42." (PMID 34341347, 2021). "Previous studies have reported abnormal levels of IL-2, IL-6, IL-7, IL-10, CRP, and tumor necrosis factor-α in COVID-19 patients." (PMID 34242179, 2021).
COVID-19 (continued). "The hyperinflammatory profiles of influenza and COVID-19 patients show similarities, e.g., high serum levels of interleukin (IL)-6 and tumor necrosis factor (TNF) alpha, and also exhibit distinct features." (PMID 34969061, 2021). "First, decreased hepatic albumin production is associated with increased release of proinflammatory mediators belonging to the COVID-19-related cytokine storm, such as IL-6 and tumor necrosis factor-alpha (TNF-alpha)." (PMID 34683480, 2021). "Recent published studies have reported that elevated inflammatory cytokine (such as TNFα, IL-1β, IL-6, IL-10, IL-17, IL-18, and IFNγ) levels were seen in active COVID-19 cases compared to healthy donors." (PMID 34348897, 2021). "Both IL-6 and TNF-α are known to be the main cytokines involved in severe symptoms’ onset in COVID-19 patients, and to be downstream of the TLR4 signalling pathway." (PMID 34564408, 2021). "The main difference in post COVID-19 versus unexposed HC were observed in IFNγ+TNFα+IL-2+ tp activated CD4+ T cells." (PMID 34322120, 2021). "Mechanistically, COVID-19–related cytokines, such as IL-6, IL-17, and TNF-a, induce oxidative stress and inflammation in endothelial and vascular smooth muscle cells, promoting micro- and macro-vascular disease." (PMID 34151246, 2021). "A unique COVID-19 inflammatory profile was previously characterized in many of these same patients and showed elevated interferons, TNF and serine proteases, and a thrombotic profile associated with endothelial activation and glycocalyx degradation." (PMID 35366258, 2021). "Several investigators reported a negative correlation between T cell numbers and the concentration of cytokines including interleukin-6 (IL-6), IL-10, interferon-γ (IFN-γ), and tumor necrosis factor-α (TNF-α) in COVID-19 patients." (PMID 34522871, 2021). "In COVID-19 patients, high concentrations of TNF-α seem to correlate with the severity of the clinical picture." (PMID 33669218, 2021). "Several studies have reported that inflammatory markers such as C-reactive protein (CRP), ferritin, interleukin (IL)-6, IL-10, and tumor necrosis factor-α (TNF-α) were significantly elevated in severe COVID-19 cases." (PMID 34408744, 2021). "Given the propensity for systemic IL-1β, TNFα, and IL-6 to contribute to peripheral and central neuronal sensitization, it can be hypothesized that the increased prevalence of neurological manifestations seen in severe COVID-19 may be associated with elevations of these cytokines." (PMID 33458558, 2021). "Both IL-6 and TNF-α are found in patients with COVID-19 and are responsible for pathological injury." (PMID 34360684, 2021). "Coffee consumption favorably correlates with inflammatory biomarkers such as CRP, interleukin-6 (IL-6), and tumor necrosis factor α (TNF-α), which are also associated with COVID-19 severity and mortality." (PMID 34203027, 2021). "We found a significantly higher serum concentration (p < 0.05) of TNF-α, IL-1β, IL-6, IL-12, IL-23, and IL-33 in patients with COVID-19 with severe disease." (PMID 34917631, 2021). "We, therefore, compared the serum levels of sTNFR1 and TNF-α upon admission to Hospital in COVID-19 patients who either required ventilation in ICU or who had milder disease." (PMID 33968010, 2021). "Taken together, these data indicate that the exogenous rhGal-9 exhibits a stimulatory function by enhancing the production of proinflammatory cytokines (e.g., IL-6 and TNF-α as the major monocyte-derived cytokines) in COVID-19 patients." (PMID 33947753, 2021). "In a meta-analysis, serum levels of interleukin-2 (IL-2), IL-2R, IL-4, IL-6, IL-8, IL-10, tumor necrosis factor-alpha (TNF-α), and interferon-gamma (INF-γ) were found to be associated with severe COVID-19 cases." (PMID 34855834, 2021).